CYP1A1 (cytochrome P450 family 1 subfamily A member 1)
Diseases named in the same sentence as CYP1A1 in open-access papers (continued):
Sharing a sentence is not in itself a finding about the gene and the disease.
Hepatic steatosis (6 papers, 2012 to 2025). Steatosis is a term used to denote lipid accumulation within hepatocytes. "Overexpression of CYP1A1 can disrupt the estrogen signaling pathway and diminish the ability of 17β-estradiol to protect against hepatic steatosis, which is marked by the buildup of TG, a pathological feature of MASLD." (PMID 40567989, 2025). "There is also evidence that the expression of CYP1A1 has protective effects against liver steatosis." (PMID 34262928, 2021). "Synthetic inulin ameliorated the change in the expression of CYP1A1 and CYP1A2 in rats fed the HF diet, in association with a suppression of the development of hepatic steatosis." (PMID 22452877, 2012). "This may have been due to the higher induction of CYP1A1 expression that occurs in the absence of Tiparp, resulting in rapid hepatic 3MC metabolism; thus, preventing hepatic steatosis." (PMID 31083300, 2019).
hypospadias (6 papers, 2018 to 2023). Hypospadias is the displacement of the urethral meatus on the ventrum of the penis. "The pathogenesis of hypospadias is viewed as multifactorial, and induced by genes polymorphisms and gene-environment interactions, hence, it is necessary to investigate the roles of interaction between CYP1A1/CYP17A1 polymorphisms and environmental risk factors." (PMID 30858503, 2019). "A positive correlation also was seen between the mRNA expression level of SRD5A2 and that of CYP1A1 in the hypospadias group." (PMID 29080015, 2018). "Among the eighteen genes, four have been previously identified in patients with hypospadias (CYP1A1, FLNA, GLI3, and GLI2), three have been reported to be associated with cryptorchidism (FLNA, RET, and PTPN11), and one has been identified in patients with micropenis (EVC)." (PMID 33424767, 2020). "The moderate and severe hypospadias groups had too few genes for this analysis, but both did show links with CYP11A1 and CYP1A1 involved in steroidogenesis of androgen." (PMID 36631595, 2023). "We then compared the expression levels of CYP1A1 and CYP1B1 between hypospadias and phimosis samples by quantitative RT-PCR analysis." (PMID 29080015, 2018). "The mRNA expression levels of CYP1A1 and CYP1B1 showed an extremely high correlation in both the hypospadias and phimosis groups." (PMID 29080015, 2018). "As far as we know, the association between maternal CYP1A1/CYP17A1 SNPs and hypospadias have not been reported in Chinese population, let alone gene-environment interaction." (PMID 30858503, 2019). "In this study, using RNA samples clinically collected from preputial tissues, we first demonstrated that the expression levels of the xenobiotic exposure marker genes, CYP1A1 and CYP1B1 correlated only in hypospadias patients but not in phimosis patients." (PMID 29080015, 2018).
Infertility (6 papers, 2013 to 2025). "A subject carrying the variants CYP1A1 Val/Val or CYP1A1 Ile/Val in association with GSTM-null genotype has a 6.90-fold higher risk for infertility than a subject carrying CYP1A1 Ile/Ile in association with a GSTM1 wild-type genotype." (PMID 26618172, 2015). "The genotypic distribution of CYP1A1*2A polymorphismin the infertile male group deviatedfrom the Hardy-Weinberg equilibrium." (PMID 28868835, 2017). "A previous study has shown a significant synergism between GSTM1 and CYP1A1 genotypes and infertility among human subjects." (PMID 26618172, 2015). "SNPs of CYP1A1 and psychological distress can alter testosterone and estrogen levels and enhance oxygen free radical formation and thus share common mechanisms to induce infertility in men." (PMID 27220890, 2016).
non-small cell lung carcinoma (6 papers, 1999 to 2025). A group of at least three distinct histological types of lung cancer, including non-small cell squamous cell carcinoma, adenocarcinoma, and large cell carcinoma.
Obesity (6 papers, 2015 to 2025). Accumulation of substantial excess body fat. "Beyond its role in ovarian toxicity, CYP1A1 functions in cholesterol and steroid synthesis and obesity upregulates the expression of CYP1A1 in animal models." (PMID 39910959, 2025). "We quantified mRNA abundance of AhR, CYP1A1 (as a marker of AhR activation) and TNF-α (as a marker of inflammation) in adipose tissue of obese mice experiencing weight loss (mice were exposed to PCB-77 during the weight-gain phase of diet-induced obesity)." (PMID 25734695, 2015).
squamous cell carcinoma (6 papers, 2000 to 2024). A carcinoma arising from squamous epithelial cells. "When cases were stratified according to histological type, there was significant association between CYP1A1*2A homozygote and squamous cell carcinoma (SCC) (odds ratio (OR) 2.86; 95% confidence interval (CI) 1.33–6.12)." (PMID 10732758, 2000). "Furthermore, the effect of onions on squamous cell carcinoma was modified by the CYP1A1 genotype, implying that the CYP1A1 may play a role in this association." (PMID 37111115, 2023). "One of which is the polymorphisms in CYP2D6 and CYP1A1 that have been studied in Egypt and Tunisia and that of CYP2D*1A, which was found to increase the risk and clinicopathological outcome of both transitional and squamous cell carcinomas in Egypt." (PMID 33659210, 2020).
steatosis (6 papers, 2018 to 2024). Increased lipid within the cytoplasm of cells. "Accordingly, the pro-steatotic effect of AHR via CYP1A1 activation had been further linked to estrogen metabolism, as estrogen degradation by CYP1A1 diminished the known protective effect of 17β-estradiol (E2) on steatosis." (PMID 34075438, 2021). "Furthermore, AhR, CYP1A1, and PPP2R2D expression in ALD patients increased with decreases in p-AMPKα as histological steatosis scores worsened." (PMID 36241614, 2022). "Regarding more specifically B[a]P metabolism, it is worth noting that neither CYP1A1 nor CYP1B1 mRNA expressions were affected by steatosis alone, in contrast to CYP1A2 whose expression was reduced." (PMID 29654281, 2018). "Furthermore, the expression levels of CYP1A1, NOCT, and TUBB6 were regulated, indicating the effects of improving the antioxidant capacity of liver tissues, reducing the steatosis of hepatocytes, and inhibiting the inflammatory reaction of hepatocytes, respectively." (PMID 35408620, 2022).
chronic kidney disease (5 papers, 2022 to 2024). Impairment of the renal function secondary to chronic kidney damage persisting for three or more months. "Specifically, the CYP1A1 *2C polymorphism has been linked to an increased susceptibility to chronic obstructive pulmonary disease (COPD) and chronic kidney disease." (PMID 39769254, 2024). "Due to poor renal excretion in patients with chronic kidney disease, the accumulation of toxic substances was found to increase CYP1A1 expression." (PMID 36668758, 2022). "On the other hand, modifying AhR and CYP1A1/2 expression/activity in particular pathological states may be a useful strategy in the therapy of chronic kidney disease and cardiovascular diseases evoked by toxic tryptophan indole metabolites." (PMID 37233670, 2023). "Human studies: In a study of more than 300 chronic kidney disease (CKD) patients and healthy controls, overexpression of polymorphic variants of CYP1A1 were associated with free radical production related enzymes after exposure to environmental pollutants, and with induction of renal dysfunction." (PMID 36668758, 2022).
chronic obstructive pulmonary disease (5 papers, 2015 to 2024). A chronic and progressive lung disorder characterized by the loss of elasticity of the bronchial tree and the air sacs, destruction of the air sacs wall, thickening of the bronchial wall, and mucous accumulation in the bronchial tree. "For example, CYP1A1 induction enhanced gefitinib-induced oxidative stress and apoptosis in A549 cells and was implicated with chronic obstructive pulmonary disease." (PMID 37737576, 2023). "Highly significant DEGs including CYP1A1, HHIP (hedgehog interacting protein), MUC5AC, and CYP2A6 might be related to the pathophysiology of chronic obstructive pulmonary disease." (PMID 38137330, 2023).
endometriosis (5 papers, 2012 to 2020). The growth of functional endometrial tissue in anatomic sites outside the uterine body. "Recent meta-analysis-based studies have investigated the relationships between polymorphisms in GSTP1, COMT, and CYP1A1 and the risk of endometriosis." (PMID 31881062, 2019). "The goal of this study was investigation of the association between MspI polymorphism of CYP1A1 gene and endometriosis in women referred to two infertility centers in Yazd, Iran who were from central and southern parts of Iran." (PMID 30643856, 2018). "Previous reports on association of MspI polymorphism of CYP1A1 gene with endometriosis are controversial." (PMID 30643856, 2018). "The aim of this study was to analyze the frequency of the MspI polymorphism of CYP1A1 gene and its relation to endometriosis." (PMID 30643856, 2018). "It was observed that CYP1A1 was implicated in metabolism of dioxin, which may increase the severity of endometriosis in rhesus monkeys." (PMID 30643856, 2018). "Therefore, considering that endometriosis is an estrogen-dependent disease, CYP1A1 may be associated with this disease." (PMID 30643856, 2018). "It is known that the genetic polymorphism of CYP1A1, CYP19, and GSTM1 enzymes, which are responsible for the metabolism of medicines, predisposes to endometriosis." (PMID 33153202, 2020). "Genetic polymorphism occurs within the endometrial tissue, concerning estrogen and progesterone receptors, as well as the polymorphism of the enzymes responsible for the metabolism of drugs (CYP1A1, CYP19, and GSTM1), predisposing to endometriosis." (PMID 33153202, 2020). "The activation of estrogen receptors in endometriosis can also be implemented indirectly via an abnormal activity of CYP1A1, CYP19, and GSTM1 polymorphic enzymes, which increase the level of P450 aromatase and estrogen production." (PMID 33153202, 2020). "Several SNPs of the estrogen synthesis- and metabolism-related genes, such as CYP19, CYP1A1 and COMT, and CYP1B1, have been found to be associated with increased risk of endometriosis." (PMID 23139742, 2012). "Besides the analysis of CYP1A1, CYP19, and GSTM1 genetic polymorphisms, the latest research concentrates on identifying the significance of the expression level of these genes in endometriosis." (PMID 33153202, 2020). "Other xenobiotic metabolic enzymes like aromatase P450 family members CYP1A1 and CYP19A1 also have a fundamental role in the pathogenesis of endometriosis, and have been widely studied and applied to endometriosis treatment." (PMID 31881062, 2019).
malignant hypertension (5 papers, 2018 to 2025). Severe hypertension that is characterized by rapid onset of extremely high blood pressure and hypertension-mediated organ damage. "In an Ang II-dependent malignant hypertension model using Cyp1a1-Ren-2 transgenic rats, blocking GPR75 with AAA effectively reversed I3C-induced malignant hypertension, which is associated with reduced Ang II levels in plasma and kidneys." (PMID 40362321, 2025). "Malignant hypertension was induced in Cyp1a1-Ren-2 transgenic rats by activation of the renin gene using indole-3-carbinol (I3C), a natural xenobiotic." (PMID 30054426, 2018). "The first important finding of the present study is that 20-HETE antagonist attenuated the development of malignant hypertension in Cyp1a1-Ren-2 transgenic rats." (PMID 30054426, 2018). "We provided evidence that the intrarenal EETs deficiency significantly contributes to the impairment of renal function and the development and maintenance of malignant hypertension in I3C-induced Cyp1a1-Ren-2 transgenic rats." (PMID 30054426, 2018). "Furthermore, we reported repeatedly that the development of ANG II-dependent malignant hypertension in Cyp1a1-Ren-2 transgenic rats is accompanied by decreased intrarenal availability of EETs." (PMID 30054426, 2018). "After dietary administration of indole-3-carbinol (I3C), the expression of the Cyp1a1 promoter is rapidly enhanced, with marked activation of Ren-2 renin gene in the liver, with subsequent increase in ANG II generation and development of ANG II-dependent malignant hypertension." (PMID 30054426, 2018). "We hypothesized that vascular actions of 20-hydroxyeicosatetraenoic acid (20-HETE), the product of cytochrome P450 (CYP450)-dependent ω-hydroxylase, potentiate prohypertensive actions of angiotensin II (ANG II) in Cyp1a1-Ren-2 transgenic rats, a model of ANG II-dependent malignant hypertension." (PMID 30054426, 2018). "Our results indicating augmented renal and peripheral vascular resistance in Cyp1a1-Ren-2 transgenic rats might suggest that prohypertensive actions of 20-HETE and its interaction with RAS importantly contribute to the pathophysiology of malignant hypertension in this model." (PMID 30054426, 2018).
non-alcoholic fatty liver disease (5 papers, 2019 to 2025). "Previous studies have shown that CYP1A1 is associated with liver injuries such as non-alcoholic fatty liver disease." (PMID 38251251, 2024). "Loss of the CYP1A1 gene protects against nonalcoholic fatty liver disease caused by a Western diet containing benzo[a]pyrene in mice." (PMID 38837944, 2024). "The involvement of AHR/CYP1A1 activation is suggested in the development of non-alcoholic fatty liver disease (NAFLD) and the consequent onset of diabetes." (PMID 38731818, 2024). "CYP1A1 is the key metabolic enzyme and target in many liver diseases, such as drug-induced liver injury and non-alcoholic fatty liver disease." (PMID 38251251, 2024). "Recent results obtained using CYP1A1(-/-) mice demonstrate that elevated expression of CYP1A1 protects against the development of non-alcoholic fatty liver disease, and dysregulation of the CYP1A1 gene is reported to be involved in the transport and metabolism of lipids." (PMID 31404079, 2019).
osteoporosis (5 papers, 2017 to 2023). A condition of reduced bone mass, with decreased cortical thickness and a decrease in the number and size of the trabeculae of cancellous bone (but normal chemical composition), resulting in increased fracture incidence. "CYP1A1’s two variants, which occur in 19% of healthy individuals, have been related to osteoporosis and Transforming growth factor beta (TGF-β) which presents polymorphisms." (PMID 35163424, 2022). "Additional genes whose mutations have been related to an increased risk of osteoporosis and fractures are Cytochrome P450 (CYP1A1) gene." (PMID 35163424, 2022). "Previous studies uncovered rare CYP1A1 mutations in osteoporosis patients who suffered AFF after long-term BP treatment." (PMID 34299011, 2021). "The two patients with the CYP1A1 VUS variants had GCC‐induced osteoporosis and had been receiving treatment with BPs for 3 and 12 years, respectively." (PMID 30680361, 2019). "Additionally, as commented on the previous page, we also observed a CYP1A1 polymorphism in another elderly patient diagnosed with postmenopausal osteoporosis who developed bilateral AFF after 9 years of BP treatment." (PMID 30680361, 2019). "Patients with CYP1A1 variants had glucocorticoid‐induced osteoporosis." (PMID 30680361, 2019). "In the current study, we investigated the role of peripheral TRP catabolism, aryl hydrocarbon receptor (AhR) as a physiological receptor for KYN and AhR-dependent cytochrome P450 1A1 (CYP1A1) in the development of osteoporosis in CKD." (PMID 29163188, 2017).
thyroid cancer (5 papers, 2008 to 2025). "A bioinformatic analysis revealed that CYP1A1 is a marker associated with prognosis and metabolism in thyroid cancer." (PMID 40693878, 2025). "Scarce data is available on the association between CYP1A1 polymorphism and increased susceptibility to thyroid cancer." (PMID 18601742, 2008). "In thyroid carcinoma patients, CYP1A1 could serve as a prognostic marker to point to the grade of tumor severity, with the CYP1A1 gene expression associated with tumor size, the presence of metastasis, and advanced clinical stage." (PMID 36685893, 2022). "In thyroid-tumor samples, the AhR target genes CYP1A1 and CYP1B1 were upregulated relative to associated healthy tissue and again Kyn stimulation of thyroid-cancer cell lines promoted the acquisition of an EMT program (decreased E-cadherin, and increased SLUG, N-cadherin, and fibronectin levels)." (PMID 33451095, 2021). "The level of AhR functional activation was evaluated by measuring CYP1A1 and CYP1B1 mRNA expression in the thyroid cancer samples." (PMID 31936153, 2020).
Alzheimer disease (4 papers, 2020 to 2025). A progressive, neurodegenerative disease characterized by loss of function and death of nerve cells in several areas of the brain leading to loss of cognitive function such as memory and language. "Thus, upregulation of miR-132-3p, miR-892a, miR-142-3p, miR-142-5p and miR-200a-3p associated with silenced activity of CYP1A1 can have therapeutic potential in Alzheimer's disease." (PMID 39812050, 2025). "Research on Alzheimer's disease revealed significant epigenetic changes in the CYP1A1 gene among AD patients." (PMID 39812050, 2025). "In Alzheimer’s disease, MNPs accelerate Aβ fibrillation and tau, disrupt lysosomal function, and enhance microglial pyroptosis (GSDMD) with impaired phagocytosis, and the effects can synergize with genotypic factors, such as APOE4 and CYP1A1 polymorphisms." (PMID 41303677, 2025). "In short, CYP1A1 appears to be induced in both Alzheimer's disease and Parkinson's disease." (PMID 39812050, 2025). "This formula could improve the cognitive function of Alzheimer’s disease through CYP1A1 and CYP3A4 metabolism-related targets." (PMID 37764767, 2023).
bladder cancer (4 papers, 2017 to 2021). "SNPs in these gene regions (AHR and CYP1A1/2) have been identified in GWAS of blood pressure, bladder cancer and Parkinson's disease, although these may be explained by downstream effects of caffeine or coffee consumption or metabolism." (PMID 27741566, 2017). "The basal PORlo bladder cancer cell lines T24 and SCaBER were used as in vitro models of POR suppression in MIBC and showed no/low inducible CYP1 enzyme activity, respectively despite CYP1A1 and CYP1B1 transcripts being ITE‐inducible." (PMID 29323757, 2018).
brain tumor (4 papers, 2010 to 2024). "Significant up-regulation of CYP1A1 has been observed in several types of malignancies, i.e. esophagus, breast, urinary bladder, and brain tumor, and is associated with poor prognosis." (PMID 27203547, 2016). "Genotyping and epidemiological studies of CYP1A1 were correlated with increased risk for brain tumor." (PMID 26580399, 2015).
breast tumor (4 papers, 2009 to 2019). "In contrast, we observed that reduced CYP1A1 expression in breast tumor cells, as observed upon contact with MΦs, correlates with enhanced proliferation of the respective tumor cells, nicely reflecting the situation found in patient samples." (PMID 30615637, 2019). "The synthetic compound Phortress or 2-(4-Amino-3-methylphenyl) benzothiazole is a CYP1A1-activated prodrug with potent in vivo activity in breast tumor xenografts." (PMID 19531241, 2009).
cardiac hypertrophy (4 papers, 2022 to 2024). "Both CYP1B1 and CYP1A1 were reported to be upregulated in the hearts of rats treated with isoprenaline-induced cardiac hypertrophy." (PMID 39188949, 2024). "Additionally, cardiac hypertrophy and impaired vascular were observed in the TCDD (a Cyp1a1 inducer)-exposed mice accompanied with the upregulation of Cyp1a1 mRNA expression and ROS accumulation in left ventricles." (PMID 35387435, 2022).